SLC5A1 (solute carrier family 5 member 1)
Description:
Electrogenic Na(+)-coupled sugar symporter that actively transports D-glucose or D-galactose at the plasma membrane, with a Na(+) to sugar coupling ratio of 2:1. Transporter activity is driven by a transmembrane Na(+) electrochemical gradient set by the Na(+)/K(+) pump. Has a primary role in the transport of dietary monosaccharides from enterocytes to blood. Responsible for the absorption of D-glucose or D-galactose across the apical brush-border membrane of enterocytes, whereas basolateral exit is provided by GLUT2. Additionally, functions as a D-glucose sensor in enteroendocrine cells, triggering the secretion of the incretins GCG and GIP that control food intake and energy homeostasis (By similarity). Together with SGLT2, functions in reabsorption of D-glucose from glomerular filtrate, playing a nonredundant role in the S3 segment of the proximal tubules (By similarity). Transports D-glucose into endometrial epithelial cells, controlling glycogen synthesis and nutritional support for the embryo as well as the decidual transformation of endometrium prior to conception. Acts as a water channel enabling passive water transport across the plasma membrane in response to the osmotic gradient created upon sugar and Na(+) uptake. Has high water conductivity, comparable to aquaporins, and therefore is expected to play an important role in transepithelial water permeability, especially in the small intestine.
Synonyms: NAGT; SGLT1; D22S675; SGLT-1
Tractability: Small molecule: an approved drug acts on it; a structure with a bound ligand is known; a high-quality ligand is known; it belongs to a druggable protein family. Antibody: UniProt places it where antibodies can reach, with high confidence; its Gene Ontology location is reachable by antibodies, with high confidence; UniProt predicts a signal peptide or a membrane-spanning region. PROTAC: a small molecule that binds it is known.
Target class: SLC superfamily of solute carriers; SLC05 family of sodium-dependent glucose transporters; Electrochemical transporter; Transporter
Chemical probes: CHEMBL2159094, CHEMBL2323695
Gene: Protein-coding gene on chromosome 22 (32,043,050 to 32,113,029, forward strand). Ensembl gene ENSG00000100170.
Subcellular location: Apical cell membrane
Subcellular location (Human Protein Atlas): Golgi apparatus; Plasma membrane; Nuclear membrane
Pathways (Reactome):
Digestion and absorption: Intestinal hexose absorption
Disease: Defective SLC5A1 causes congenital glucose/galactose malabsorption (GGM)
Transport of small molecules: Cellular hexose transport
Gene Ontology:
Molecular function: alpha-glucoside transmembrane transporter activity; D-glucose transmembrane transporter activity; D-glucose:sodium symporter activity; galactose:sodium symporter activity; protein binding; water transmembrane transporter activity; fucose transmembrane transporter activity; galactose transmembrane transporter activity; myo-inositol:sodium symporter activity; pentose transmembrane transporter activity; solute:sodium symporter activity; transmembrane transporter activity
Biological process: alpha-glucoside transport; chloride transmembrane transport; D-glucose import across plasma membrane; D-glucose transmembrane transport; sodium ion import across plasma membrane; transepithelial water transport; transport across blood-brain barrier; fucose transmembrane transport; galactose transmembrane transport; intestinal D-glucose absorption; intestinal hexose absorption; myo-inositol transport; pentose transmembrane transport; renal D-glucose absorption; transmembrane transport
Cellular component: apical plasma membrane; early endosome; extracellular exosome; perinuclear region of cytoplasm; plasma membrane; brush border membrane; intracellular vesicle; membrane
Genetic constraint (gnomAD): Loss-of-function variants: 36 observed, 67.4 expected, observed/expected ratio (o/e) 0.53, 90% interval 0.41 to 0.7. The upper end of that interval is the gene's LOEUF score, 0.7, which puts it in group 2 of 6, group 1 being the genes least tolerant of losing a copy. Missense variants: 618 observed, 872.32 expected, observed/expected ratio (o/e) 0.71, 90% interval 0.66 to 0.76. Synonymous variants: 294 observed, 327.69 expected, observed/expected ratio (o/e) 0.9, 90% interval 0.81 to 0.99.
Homologues: Orthologues: chimpanzee SLC5A1 (99% identical), macaque SLC5A1 (96% identical), mouse Slc5a1 (88% identical), rat Slc5a1 (88% identical), pig SLC5A1 (87% identical), dog SLC5A1 (87% identical), rabbit SLC5A1 (84% identical), guinea pig SLC5A1 (84% identical), tropical clawed frog slc5a1.1 (74% identical), zebrafish slc5a1 (72% identical), Drosophila melanogaster CG2187 (17% identical), Drosophila melanogaster Smvt (16% identical), and 8 more. Paralogues in human: SLC5A4 (70% identical), SLC5A2 (59% identical), SLC5A9 (55% identical), SLC5A11 (52% identical), SLC5A10 (49% identical), SLC5A3 (47% identical), SLC5A8 (20% identical), SLC5A12 (20% identical), SLC5A5 (19% identical), SLC5A6 (18% identical), SLC5A7 (15% identical).
Diseases named in the same sentence as SLC5A1 in open-access papers:
SLC5A1 is named in the same sentence as 164 diseases in open-access papers, as found by Europe PMC text mining. Sharing a sentence is not in itself a finding about the gene and the disease. The quoted sentences say what the papers report.
diabetes (118 papers, 2009 to 2026). "Sglt1 (also known as Slc5a1) and Sglt2 (also known as Slc5a2) knockout mice were employed to develop sotagliflozin, a dual SGLT1/SGLT2 inhibitor having success in clinical trials for diabetes." (PMID 31064765, 2019). "SLC2A9 and SLC5A1 are both glucose transporters over the cell membrane and are as such interesting candidate genes for diabetes." (PMID 19575795, 2009). "SGLT1 (SLC5A1) is a key glucose transporter regulating glucose absorption in the gastrointestinal tract, and is considered a potential target for treating obesity and diabetes." (PMID 36014921, 2022). "However, neither SLC2A9 nor SLC5A1 has been shown to be closely associated with diabetes and this is reflected in the descriptive text in OMIM, which is very brief." (PMID 19575795, 2009). "Moreover, the dysregulation of the sodium-dependent glucose transporter (SGLT1 or SLC5A1) in the intestinal epithelium, controlled by ACE2, has been linked to the pathogenesis of diabetes mellitus, which may contribute to the higher mortality observed in COVID-19 patients with diabetes." (PMID 38813031, 2023). "Co-treatment substantially reduced the diabetes-induced upregulation of Slc2a2, but not Slc5a1 and Slc5a2, mRNA levels when compared to all other diabetic arms." (PMID 27226136, 2016).
type 2 diabetes (56 papers, 2012 to 2026). "A Mendelian randomization study examining the missense variants in SLC5A1, which is associated with a decrease in SGLT1 function, has shown decreased incidence of type 2 diabetes, obesity, heart failure, and death." (PMID 34750713, 2022). "Six genes (CNR2, DPP4, GLP1R, SLC5A1, HTR2C, MCHR1) that encode therapeutic targets in development of type 2 diabetes or obesity." (PMID 36902588, 2023).
heart failure (37 papers, 2018 to 2025). Inability of the heart to pump blood at an adequate rate to meet tissue metabolic requirements. "Heterozygosity for the missense variants in SLC5A1 (solute carrier family 5 member 1), which cause decreased SGLT1 function, was associated with decreased incidence of heart failure and death, as well as T2D." (PMID 37109553, 2023). "SLC5A1 inhibition can protect against myocardial infarction-induced ventricular remodeling and heart failure in mice by replenishing ATP stores in ischemic cardiac tissues by enhancing glucose availability." (PMID 34540994, 2021).
Obesity (32 papers, 2014 to 2026). Accumulation of substantial excess body fat. "It has been proposed that SGK1 promotes obesity by stimulating the Na+ glucose cotransporter SGLT1 (solute carrier family 5 member 1)." (PMID 35456474, 2022). "However, there are reports on six of Slc genes (Slc2a10, Slc5A1, Slc5a9, Slc6A14, Slc16A5, Slc25A24) in metabolic diseases including obesity, dyslipidemia, NAFLD, and T2DM." (PMID 34659115, 2021).
pancreatic cancer (11 papers, 2010 to 2025). "The prognostic value of SLC5A1 has also been illustrated by the significant association between the high expression of SLC5A1 in pancreatic cancer and the disease‐free survival (DFS) of patients." (PMID 33783998, 2021). "SLC5A1 has been confirmed to be highly expressed in many malignant tumors by several studies, including our research, and a study on pancreatic cancer demonstrated that SLC5A1 regulates cancer cell growth through AMPK/mTOR signaling." (PMID 40963858, 2025). "SLC5A1 promotes growth and proliferation of pancreatic cancer." (PMID 32260415, 2020).
diabetic cardiomyopathy (9 papers, 2015 to 2025). Diabetic cardiomyopathy is a disorder of the heart muscle in people with diabetes. "However, over-expression of SGLT1 (SLC5A1 gene) has been described in patients with ischemic cardiomyopathy and diabetic cardiomyopathy." (PMID 36297433, 2022).
glucosuria (8 papers, 2007 to 2025). "Indeed, we observed glucosuria in Stx2-injected mice that reproduces other study with Stx1-injected mice indicating SGLT1 (SLC5A1) dysfunction in the proximal tubules." (PMID 35202097, 2022).
prostate carcinoma (8 papers, 2010 to 2022). A carcinoma that arises from epithelial cells of the prostate gland. "Aberrant expression of SLC5A1 in different types of human cancers is observed, including ovarian cancer, cervical cancer, colorectal cancer, hepatocellular carcinoma,prostate cancer." (PMID 35361267, 2022).
colorectal cancer (7 papers, 2014 to 2025). A primary or metastatic malignant neoplasm that affects the colon or rectum. "SLC5A1 is upregulated in colorectal cancer and associated with an advanced clinical stage of the disease 14, indicating a potential role for SLC5A1 in colon cancer." (PMID 39781340, 2025). "The expression of selected genes related to MG degradation III (AKR1B10, AKR1C2 and ADH4), glyoxalase system (GLO1 and HAGH), glucose transport (SLC2A1 and SLC5A1) and colorectal cancer-associated genes (AREG, CXCL8 and CEACAM1) were quantitated using qRT-PCR." (PMID 32561807, 2020). "The SLC5A1 expression profile obtained from the GEPIA 2.0 online database demonstrated that SLC5A1 is significantly expressed in colorectal cancer." (PMID 39781340, 2025). "We performed proliferation, migration, and invasion tests to better understand the effect of Hesperidin on the malignant progression of colorectal cancer through regulating SLC5A1." (PMID 39781340, 2025).
ovarian carcinoma (7 papers, 2014 to 2022). A malignant neoplasm originating from the surface ovarian epithelium. "High expression of SGLT1, which is encoded by SLC5A1, is associated with tumor development and poor prognosis in ovarian cancer." (PMID 32260415, 2020).
Cognitive impairment (4 papers, 2020 to 2025). Abnormal cognition is characterized by deficits in thinking, reasoning, or remembering. "For instance, Slc5a1 (also known as Sglt1), the top down‐regulated gene in MONW‐Lep animals, encodes a sodium‐glucose cotransporter whose inhibition protects against cognitive impairment in mice." (PMID 40944384, 2025). "The pathological role of SLC5A1 is not well known, but cognitive impairment and damage to hippocampal neurons after chronic brain hypoperfusion were reduced in Slc5a1 knockout mice." (PMID 39364042, 2024).
Hyperinsulinemia (4 papers, 2019 to 2025). An increased concentration of insulin in the blood. "In vivo hyperinsulinemia and in vitro exposure of cardiomyocytes to high glucose or insulin led to an increase in SGLT1 expression by increasing binding of the transcription factors HNF-1 and Sp1 to the SGLT1 gene (Slc5a1), and the transcript stabilizer HuR to SGLT1 mRNA." (PMID 40932483, 2025).
colon carcinoma (3 papers, 2011 to 2025). "Besides, we investigated the association between SLC5A1 mRNA expression levels and clinicopathologic features of patients with colon cancer." (PMID 39781340, 2025). "SwissTarget Prediction and TargetNet forecast indicate that SLC5A1 is the only target with a binding probability exceeding 0.05, consistently identified in both databases, exhibiting expression changes in colon cancer cells treated with Hesperidin." (PMID 39781340, 2025). "SLC5A1 expression level was decreased in colon cancer cells treated with varying concentrations of Hesperidin compared to those in the control group." (PMID 39781340, 2025). "These in vitro cell experiments indicate that elevated SLC5A1 levels are essential for colon cancer cell proliferation, migration, and invasion." (PMID 39781340, 2025). "Upon administering EGF to SLC5A1 knockdown colon cancer cells, the EGFR phosphorylation level was restored." (PMID 39781340, 2025). "The findings revealed that Hesperidin inhibits colon cancer proliferation, migration, and invasion by regulating SLC5A1." (PMID 39781340, 2025). "Simultaneously, SLC5A1 overexpression can significantly promote colon cancer cell proliferation, migration, and invasion and inhibit the anticancer effect of Hesperidin." (PMID 39781340, 2025). "We identified a direct SLC5A1-EGFR interaction essential for regulating EGFR activity in colon cancer." (PMID 39781340, 2025). "Our findings were significantly restored following SLC5A1 overexpression in colon cancer cells, highlighting its pivotal role in Hesperidin-induced responses." (PMID 39781340, 2025). "Herein, we verified the inhibitory effect of Hesperidin on colon cancer cell proliferation, migration, and invasion by downregulating SLC5A1 and inhibiting EGFR phosphorylation." (PMID 39781340, 2025). "The results revealed that overexpression of SLC5A1 significantly enhanced the proliferation, migration, and invasion of colon cancer cells, an effect reversed upon the administration of Hesperidin to SLC5A1 overexpressing colon cancer cells." (PMID 39781340, 2025). "Based on these observations, we propose that Hesperidin exerts its anticancer effects in colon cancer cells by downregulating SLC5A1 expression, which diminishes EGFR phosphorylation." (PMID 39781340, 2025). "Our findings indicate that the ability of Hesperidin to prevent colon cancer may depend on the suppression of SLC5A1 expression, which inhibits EGFR phosphorylation." (PMID 39781340, 2025). "SLC5A1-mediated migration and invasion of colon cancer cells were further investigated." (PMID 39781340, 2025). "Further research found that SLC5A1 is highly expressed in colon cancer." (PMID 39781340, 2025). "We subsequently evaluated whether EGF could reverse the inhibitory effects of SLC5A1 downregulation on colon cancer cell proliferation, invasion, and migration." (PMID 39781340, 2025). "Accordingly, we hypothesized that EGFR may be downstream of SLC5A1, affecting colon cancer cell migration and invasion." (PMID 39781340, 2025). "However, the knockdown of the HCT-116 and DLD-1 colon cancer cell lines (sh-SLC5A1) resulted in a decrease in the proliferative capacity of the cells." (PMID 39781340, 2025). "Western blotting revealed that the expression of the biomarkers of EMT, N-Cadherin, Vimentin, and Snail was downregulated or upregulated after SLC5A1 knockdown or overexpression, which further demonstrated that SLC5A1 could regulate colon cancer cell migration and invasion." (PMID 39781340, 2025). "Therefore, we hypothesized that Hesperidin, through SLC5A1, regulates the malignant progression of colon cancer." (PMID 39781340, 2025). "Moreover, we established two stable colon cancer cell lines that overexpress SLC5A1 (oe-SLC5A1)." (PMID 39781340, 2025). "To investigate how SLC5A1 influences colon cancer proliferation, migration, and invasion, we utilized the STRING database to predict potential proteins interacting with SLC5A1." (PMID 39781340, 2025).
colon carcinoma (continued). "In addition, we observed that compared to the NC group, SLC5A1 knockdown could suppress the proliferation, migration, and invasion of colon cancer cells, while SLC5A1 overexpression could suppress the inhibitory effect of Hesperidin on colon cancer cells." (PMID 39781340, 2025). "Because of the high SLC5A1 expression in colon cancer cells, we inhibited endogenous SLC5A1 expression in HCT116 and DLD1 cells using the lentiviral SLC5A1 vector specifically targeting SLC5A1 (sh-SLC5A1)." (PMID 39781340, 2025). "Consequently, we hypothesized that SLC5A1 may regulate the EGFR phosphorylation level, thereby influencing the proliferation, migration, and invasion of colon cancer." (PMID 39781340, 2025).
Fanconi-Bickel syndrome (3 papers, 2011 to 2020). "Genetic variants of transporters contributing to intestinal sugar transport are associated with human diseases, such as glucose-galactose malabsorption and Fanconi-Bickel syndrome caused by mutations in SGLT1 (SLC5A1) and GLUT2 (SLC2A2), respectively." (PMID 33015026, 2020).
Impaired glucose tolerance (3 papers, 2021 to 2022). An abnormal resistance to glucose, i.e., a reduction in the ability to maintain glucose levels in the blood stream within normal limits following oral or intravenous administration of glucose. "In human, Slc5a1 expression is increased in the duodenal of individuals with impaired glucose tolerance and T2DM." (PMID 34659115, 2021).
chronic rhinosinusitis (2 papers, 2017 to 2019). Chronic form of sinusitis. "Our study indicates that HLCS, HLA-DRA, BICD2, VSIR and SLC5A1 could be involved in the pathogenesis of chronic rhinosinusitis with nasal polyps." (PMID 29253858, 2017). "HLA-DRA has been associated with chronic rhinosinusitis with nasal polyps in previous studies and HLCS, BICD2, VSIR and SLC5A1 may be new targets for future research." (PMID 29253858, 2017). "This study suggests that HLA-DRA as well as four additional genes; HLCS, VSIR, BICD2 and SLC5A1, which have not been previously identified as associated with chronic rhinosinusitis with nasal polyps, could be important for the development of this disease." (PMID 29253858, 2017). "Comparisons with data from expression quantitative trait loci showed the most skewed allelic distributions in cases with chronic rhinosinusitis with nasal polyps compared with controls for the genes HLCS, HLA-DRA, BICD2, VSIR and SLC5A1." (PMID 29253858, 2017).
glucose-galactose malabsorption (2 papers, 2016 to 2025). Glucose-galactose malabsorption (GGM) is a very rare, potentially lethal, genetic metabolic disease characterized by impaired glucose-galactose absorption resulting in severe watery diarrhea and dehydration with onset inthe neonatal period. "Glucose-galactose malabsorption (GGM, OMIM 606824) is a rare autosomal recessive disorder caused by a defect in the solute carrier family 5 member 1 gene SLC5A1, which codes for a Na+/glucose co-transporter." (PMID 26978392, 2016).
malabsorption syndrome (2 papers, 2011 to 2021). A syndrome resulting from the inadequate absorption of nutrients in the small intestine. "In addition, we have identified the mutation in the SGLT1 (SLC5A1) gene responsible for the malabsorption syndrome, Q457R, in 8 cases." (PMID 34485913, 2021).
asthma (1 paper, 2017). "HLCS, BICD2, and SLC5A1 have not been connected to asthma, VSIR was implicated with lung function decline in non-asthmatic patients in a genome-wide study published in 2012 but this association could not be confirmed by replication." (PMID 29253858, 2017).
brain tumors (1 paper, 2022). "Biopsy analysis of GBM also revealed expression of the proteins SLC5A1 and SLC5A3 in brain tumors." (PMID 36497276, 2022).
glioma (1 paper, 2022). A benign or malignant brain and spinal cord tumor that arises from glial cells (astrocytes, oligodendrocytes, ependymal cells). "SLC5A1, which encodes a member of the sodium-dependent glucose transporter, promotes ferroptosis, an alternative pathway of cell death that can be targeted to reverse TMZ resistance in glioma." (PMID 36499683, 2022).